HIF1A (hypoxia inducible factor 1 subunit alpha)
Diseases named in the same sentence as HIF1A in open-access papers (continued):
Sharing a sentence is not in itself a finding about the gene and the disease.
breast cancer (continued). "The relative expression of cell stress related proteins, and in particular, the differential expression of HIF1α observed after 6 or 24 hours of hypoxic conditioning led to the choice of these time points for uptake studies in MDA-MB-231 human breast cancer cells." (PMID 30120388, 2018). "One mechanism through which Parkin may help suppress metastasis is by ubiquitinating HIF-1α and triggering its degradation, thereby inhibiting the migration and invasion of breast cancer cells." (PMID 29941042, 2018). "Recently, a comprehensive overview of HIF-1α action on ERα expression and function was provided in a selected panel of ER-positive breast cancer cells, which were representative of the diverse genetic backgrounds and mutational landscape commonly observed in ER-α positive tumors." (PMID 29996493, 2018). "Interestingly, a functional cooperation between HIF-1α and GPER in breast cancer cells and in breast cancer associated fibroblasts was shown to regulate the hypoxia-dependent VEGF expression toward tumor angiogenesis and progression." (PMID 29996493, 2018). "Furthermore, we describe the role of hypoxia signaling in breast cancer cells and discuss recent evidence regarding a functional interaction between HIF-1α and GPER in both breast cancer cells and cancer-associated fibroblasts (CAFs)." (PMID 29996493, 2018). "Immunohistochemical analysis of HIF-1α protein levels in primary breast cancer biopsies has demonstrated a significant association with mortality in several clinical studies, showing the importance of HIF-1α in breast cancer progression." (PMID 29628507, 2018). "Notably, in breast cancer cells lines, HIF-1α has been reported to repress transcription of the estrogen hormone receptor, ERα, and V-ATPase inhibition was reported to increase HIF-1α protein levels in several other cancer cell lines." (PMID 29988966, 2018). "Importantly, analysis on knock-in mice expressing a methylation-resistant HIF-1α mutant protein confirmed that lysine demethylation is a crucial mechanism regulating hypoxia-induced stability of HIF-1α in breast cancer." (PMID 29996493, 2018). "In addition, treatment with P4HA inhibitor 1,4-dihydrophenonthrolin-4-one-3-carboxylic acid (1,4-DPCA) or ethyl-3,4-dihydroxybenzoic acid decreased HIF-1α protein levels in breast cancer cells." (PMID 30367042, 2018). "Finally, they demonstrated that WWOX expression inversely correlates with HIF1α target gene Glucose transporter 1 gene (Glut1) in breast cancer tissue samples." (PMID 30619734, 2018). "Interestingly, HIF1α is known to be highly activated in triple-negative breast cancer (TNBC), a subset of aggressive breast cancers most of which are high-grade and present a high risk of metastasis and recurrence." (PMID 30180888, 2018). "Interestingly, a recent study revealed that the expression of CD47 is transcriptionally regulated in breast cancer cells by HIF1α." (PMID 29707136, 2018). "The reciprocal regulation of HIF1α and HIF2α was observed in primary breast cancer cells and in MDA-MB-231 cells after 72 h of Jagged1-stimulation, as well as in Notch-activated medulloblastoma D324 cells when cells were treated with CoCl2, a frequently utilized hypoxia-mimetic." (PMID 29993038, 2018). "In addition, IL-6 derived from metastatic CAFs triggered breast cancer growth in vitro and in vivo through the involvement of Notch-3, Jagged-1, and the HIF-1α target gene carbonic anhydrase IX." (PMID 29996493, 2018). "Furthermore, similar tissue specificity has been observed for HIF-1α, which acts as tumor suppressor in renal cancer, but as a tumor promoter in breast cancer." (PMID 29784889, 2018). "There are a number of micro RNAs that act as inhibitors of HIF-1α in healthy tissues but are downregulated in cancers allowing for an increase in HIF-1α expression such as miR-33b which is downregulated in osteosarcoma and oncosuppressive in breast cancer tissues." (PMID 29098360, 2018).
breast cancer (continued). "In addition, we also observed a correlation of TP53INP1 expression with the expression of HIF1‐α in breast cancer by Pearson analysis (r = −.0293, P = .003)." (PMID 29655255, 2018). "Moreover, hypoxia/HIF1α induces lapatinib resistance in HER2-positive breast cancer cells via regulation of DUSP2 and HIF-1 can bypass the lapatinib-treated inhibition of the ERK pathway via inhibition of the dual-specificity phosphatase 2 (DUSP2)." (PMID 29410730, 2017). "We then investigated whether Parkin inhibits migration and invasion of human breast cancer cells through its downregulation of HIF-1α." (PMID 29180628, 2017). "HIF-1α and HIF-2α are linked to breast cancer metastasis and poor patients’ survival." (PMID 28993797, 2017). "Higher expression of HIF-1α is correlated with poorer survival in breast cancer patients." (PMID 27906669, 2017). "Interestingly, some of these genes have also been linked to cancer progression, for example HIF1A-dependent upregulation of PDGFB and ANGPTL-4 promotes metastasis of hypoxic breast cancer cells." (PMID 28077088, 2017). "Similarly, ectopic Myc-Parkin downregulated endogenous HIF-1α levels in different breast cancer cells and MCF10A cells." (PMID 29180628, 2017). "Overall, our study provides novel evidence regarding the angiocrine action elicited by IGF1 in breast cancer through the activation of HIF-1α/VEGF signaling pathway, emphasizing the important role played by GPER in the modulation of this relevant transduction axis." (PMID 29212519, 2017). "We next examined the relationship between HIF-1α levels and CA in breast cancer samples." (PMID 28272508, 2017). "HIF-1α and its target genes play a strong role in driving breast cancer cell proliferation." (PMID 28993797, 2017). "Thus, our results provide evidence that Parkin inhibits breast cancer metastasis through downregulation of HIF-1α." (PMID 29180628, 2017). "We then investigated whether negative regulation of HIF-1α mediates Parkin’s function in suppressing lung metastasis of breast cancer cells in vivo." (PMID 29180628, 2017). "For example, several factors modulate pVHL activity, such as WD repeat and SOCS box-containing protein 1 (WSB1), which was found to promote HIF-1α stabilization and metastases via ubiquitination and degradation of pVHL in renal carcinoma, breast cancer, and melanoma models." (PMID 29230384, 2017). "Similarly as in a previous study, isoliquiritigenin was found to significantly inhibit VEGF expression in breast cancer cells via promoting HIF-1α proteasome degradation, and directly interacted with VEGFR-2 to block its kinase activity." (PMID 29271940, 2017). "We find that stabilized HIF-1α induces rapid loss of ER-α protein in all members of our diverse panel of breast cancer cell lines, which involves proteolysis rather than transcriptional repression." (PMID 28320353, 2017). "Notably, C431A, T173A, T240M and P294S mutations of Parkin that inhibit Parkin’s E3 ligase activity for HIF-1α significantly impaired the ability of Parkin to inhibit migration and invasion of breast cancer cells." (PMID 29180628, 2017). "Importantly, Parkin expression is inversely correlated with HIF-1α expression and metastasis in breast cancer." (PMID 29180628, 2017). "Similarly, high PGC1α and HIF1α levels have been suggested as effective and non-invasive plasma biomarkers of poor prognosis for patient with breast cancer." (PMID 28947972, 2017). "Clinical studies in breast cancer suggest important associations between intratumoral hypoxia, the upregulation of epidermal growth factor receptor (EGFR or HER1), hypoxia-inducible factor 1α (HIF-1α), and reduced patient survival." (PMID 28038470, 2017). "The correlation between the Parkin expression and HIF-1α levels was investigated in three different cohorts of human breast cancer specimens in three TMAs, including TMA-RCINJ from the Rutgers Cancer Institute of New Jersey (RCINJ), and TMA-BR2082a and TMA-BR2281 from US Biomax." (PMID 29180628, 2017).
breast cancer (continued). "Thus, pro-tumorigenic effects of HIF-1α activation have been observed in breast cancer, consistent with the reported restriction of breast cancer growth by BHLHE41 through down-regulation of HIF-α." (PMID 28715484, 2017). "An oncogenic role of HIF-1α in breast cancer has been well characterised." (PMID 28536364, 2017). "Furthermore, SIRT3 also suppresses HIF1-α and its targeted genes as has been demonstrated in human colon carcinoma, osteosarcoma cells and breast cancer cells." (PMID 29212260, 2017). "Notwithstanding hypoxia downregulates Wwox in different cell types as in 1833-bone metastatic cells, derived from MDA-MB231 breast carcinoma cells, only in 1833 cells exogenous Wwox stabilizes HIF-1α: the latter effect is more pronounced under moderate hypoxia." (PMID 28045433, 2017). "Finally, breast cancer dataset analysis confirms a strong correlation of MCU expression with HIF‐1α signaling." (PMID 27138568, 2016). "We next analyzed the expression of ALKBH5 and HIF-1α in human breast cancer biopsies." (PMID 27590511, 2016). "So far, only several reports looked at HIF-1α plasma level in breast cancer as a prognostic factor." (PMID 27780920, 2016). "HIF-1α also directly regulates the expression of TWIST in breast cancer cells." (PMID 27706047, 2016). "Moreover, immunohistochemistry staining of the breast cancer tumors formed in vivo indicate that hnRNP A18 accumulates in the hypoxic region of the tumor as defined by HIF-1α staining." (PMID 26824423, 2016). "Thus, previous data and the present study strongly implicated that miR-101 mediated inhibition on cell proliferation in breast cancer cells seems due to HIF1α-induced apoptosis and cell cycle arrest." (PMID 26841847, 2016). "Some researches demonstrated that the plasma level of HIF-1α is high in breast cancer patients." (PMID 27780920, 2016). "In breast cancer cohort, both HIF-1α and PGC-1α plasma levels were closer to a normal distribution." (PMID 27780920, 2016). "Interestingly, a majority of YBX1 and HIF1A positive populations in ER−/low breast cancers are also ST14/Prss14 high expressors." (PMID 27167193, 2016). "In contrast, HIF-1α was barely detectable in the cultures from the mammary tumor cell line." (PMID 27105499, 2016). "Further, experimental studies indicate that HER2 signaling is implicated in up-regulation of VEGF via mediators such as HIF-1α transcription factor to promote tumor angiogenesis, and HIF-1α expression correlated with the HER2 subtype and HER2 positivity in breast cancers." (PMID 26760782, 2016). "One of important findings in our study is that the interaction of fibroblasts-breast cancer cells could stimulate HIF-1α expression." (PMID 27325313, 2016). "Indeed, upregulation of HIF-1α expression is observed in multiple cancers, including colon cancer, breast cancer, prostate cancer, chronic myelogenous leukemia, glioblastoma, rhabdomyosarcoma, and leukemia." (PMID 27144516, 2016). "HIF target genes include many metastasis-related gene products which may provide the mechanistic clues that support studies over the past decade that demonstrate a role for HIF-1α in adverse outcomes in breast cancer patients." (PMID 27706047, 2016). "However, the mechanisms of increased HIF-1α abundance, and its role in regulating breast cancer plasticity are not fully understood." (PMID 27058900, 2016). "Moreover, HIF-1α was able to contribute to endocrine therapy resistance to ERα (+) breast cancer cells." (PMID 27429011, 2016). "Therefore, our results demonstrate that metabolic regulation, with succinate and/or fumarate accumulation, governs the dynamic transition of breast cancer tumorigenic states and we suggest that HIF-1α is indispensable for breast cancer tumorigenicity." (PMID 27058900, 2016). "The results showed that HIF-1α could increase the percentage of breast cancer stem like cells via STAT3." (PMID 27325313, 2016). "Lower ERα expressions were determined in HIF-1α positive breast cancers than in HIF-1α ones." (PMID 27821168, 2016).
breast cancer (continued). "The frequent presence of tumor hypoxia, HIF1α, and HIF2α in solid tumors, including breast cancer, suggests that these tumor areas may possess inherent antiestrogen resistance that can withstand therapy and contribute to treatment failure." (PMID 26849233, 2016). "Immunohistochemical studies in tumor biopsies have linked increased HIF-1α protein levels with an increased risk of metastasis and mortality in lymph node-positive, lymph node-negative, Her2+, ER+, and unselected breast cancer patients." (PMID 27187355, 2016). "Our data demonstrate that breast cancer patients have higher levels of both HIF-1α and PGC-1α." (PMID 27780920, 2016). "Regardless of lymph node involvement in breast cancer, survival outcomes are significantly decreased in patients with the highest HIF-1α levels in their diagnostic breast cancer biopsies." (PMID 27706047, 2016). "The role of HIF-1 transcription factor varies during breast carcinoma progression, and this might be also related to the complex regulation of HIF-1α subunit." (PMID 27187355, 2016). "R. algida might exert an anti-carcinogenic effect on MCF-7 breast cancer cells by decreasing the protein levels of HIF-1α and HIF-2α, which are overexpressed under hypoxic conditions." (PMID 26279639, 2015). "To confirm this hypothesis, we developed the HIF-1α stably expressing ERα-positive human breast cancer cell line, MCF-7/HIF-1α, and successfully established xenografts in nude mice." (PMID 25929338, 2015). "Ki67 and HIF-1α are commonly viewed as the markers of poor prognosis in breast cancer." (PMID 26512778, 2015). "Thus, we conclude that HBXIP upregulates miR-183/96/182 through transcriptional factor HIF1α in breast cancer cells." (PMID 26309161, 2015). "Thus, we conclude that miR-183 enhances the stability of HIF1α through targeting VHL mRNA CDS in breast cancer cells." (PMID 26309161, 2015). "Indeed, the expression of a stable HIF-1α mutant or reduction of DUSP2 via RNAi can promote lapatinib resistance in breast cancer cells under normal oxygen tension." (PMID 25596742, 2015). "Consistently, silencing HIF-1α abrogated TGF-β1-induced breast cancer cell invasion." (PMID 26520789, 2015). "Moreover, we identified that HBXIP was able to upregulate miR-183/96/182 through activating its promoter involving transcriptional factor HIF1α in breast cancer cells." (PMID 26309161, 2015). "In addition, our data indicate potential double prognostic meaning of HIF-1α expression in breast cancer and necessitate focused studies, taking into account the immunophenotype interactions and tissue heterogeneity aspects." (PMID 26512778, 2015). "HIF-1α is a determinant of resistance to endocrine therapy and should be considered as a potential therapeutic target for overcoming endocrine resistance in estrogen receptor (ER)-positive breast cancer." (PMID 25929338, 2015). "Given that BRCA1-associated breast cancers often belong to the TNBC subtype, and both frequently show morphologic evidence of hypoxia (central fibrosis and necrosis), an augmented expression of HIF-1α in tumors with a triple-negative phenotype was anticipated." (PMID 26046764, 2015). "In this study, we investigated the hypothesis that HIF-1α expression contributes to the resistance to endocrine therapy in breast cancer." (PMID 25929338, 2015). "In addition, HIF-1α was verified to be required in HER2/neu (ERBB2)-mediated mammary tumor growth and anoikis resistance." (PMID 25997612, 2015). "HBXIP is able to upregulate the HIF1α expression through FGF8/PI3K/Akt signaling in breast cancer." (PMID 26309161, 2015). "We established MCF-7 breast cancer subclones, which were stably transduced with lentiviral vectors encoding NTC shRNA or shRNA targeting HIF-1α (sh1α), HIF-1β (sh1β), or TAZ (shT1), and immunoblot assays confirmed effective knockdown of HIF-1α and TAZ as well as HIF-1β protein expression." (PMID 26059435, 2015).
breast cancer (continued). "In line with recent studies from our group that elucidated that interference of Archazolid with the iron metabolism leads to S-phase cell cycle arrest in breast cancer, Archazolid A stabilized Hif1α in leukemic cells which was abrogated by simultaneous treatment with iron citrate." (PMID 26496038, 2015). "Therefore, inhibition of EMT of breast cancer cell by TEPA is most likely through de-stabilization of HIF-1α and thus down-regulation the expression of Snail and Twist." (PMID 26174737, 2015). "In a study investigating the role of both HIF-1α and HIF-2α in breast cancer patient survival, HIF-2α but not HIF-1α was identified as an independent prognostic factor associated with reduced recurrence-free and breast cancer-specific survival." (PMID 26305551, 2015). "Next, we examined whether HBXIP activated miR-183/96/182 promoter through interaction with HIF1α in breast cancer cells." (PMID 26309161, 2015). "For example, inhibition of HIF-1α by YC-1 decreased proliferation and metastasis in breast cancer." (PMID 25929338, 2015). "Since hypoxia increased Snail and TWIST1 expression, we next determined whether HIF-1α is implicated in TGF-β1-induced Snail and TWIST1expression in breast cancer cells." (PMID 26520789, 2015). "Additionally, HIF-1α overexpression is associated with increased VEGF expression in many different types of cancer such as; breast cancer, colon cancer and hepatocellular carcinoma." (PMID 26526196, 2015). "In metastatic breast cancer and melanoma cells, expression of four of the proteins affected by methyl sulfone (HIF-1α, PKM2, GLUT1 and VEGF) was hypoxia-dependent suggesting that at least initial regulation of these proteins by methyl sulfone occurred via HIF-1α." (PMID 26536104, 2015). "As observed in this study, HIF-1α is overexpressed in the majority of advanced breast cancers." (PMID 25929338, 2015). "Finally, inhibition of the Akt/mTOR pathway resulted in less accumulation of lactate in the LCC2 cells and glycolysis inhibition induced repression of Akt/mTOR/HIF-1α axis in tamoxifen-resistant breast cancer cell-specific manner." (PMID 26158266, 2015). "Therefore, a feedback loop of HIF1α/miR-183/pVHL/HIF1α modulated by HBXIP contributes to the glucose metabolism reprogramming in breast cancer cells." (PMID 26309161, 2015). "Furthermore, we identified that HBXIP disassociated the interaction of HIF1α with pVHL in breast cancer cells." (PMID 26309161, 2015). "The most importantly, this is the first report to demonstrate that alterations in glucose metabolism are revealed in tamoxifen-resistant breast cancer cells and that the HIF-1α pathway and Akt/mTOR oncogenic signaling molecules are associated with the Warburg effect in these cells." (PMID 26158266, 2015). "NCOA1 works not only with both HIF1α and AP-1 to upregulate VEGFa expression as shown in this study but also works with different transcription factors to upregulate different target genes to promote breast cancer progression and metastasis." (PMID 26287601, 2015). "HIF-1α expression predicts poor therapeutic response and clinical outcome in human breast cancers and contributes to resistance to the tyrosine kinase inhibitor Lapatinib in ErbB2-positive breast cancer cells." (PMID 26405162, 2015). "The levels of miR-373, TXNIP, HIF1α and TWIST were significantly associated with the TNM stage and lymph node metastasis, but not with other tested clinical characteristics in patients with breast cancer." (PMID 26196741, 2015). "In addition, in human endothelial cells, the conditioned medium from breast cancer cells treated with CuSO4 promoted cell migration and tube formation through HIF-1α and GPER." (PMID 26415222, 2015). "Moreover, AMPK activation induced by AMPK activator negatively regulates the glycolysis-dependent metabolism in tamoxifen-resistant breast cancer cells by inhibiting mTOR/HIF-1α signaling." (PMID 26158266, 2015).